RNU1-41P (RNA, U1 small nuclear 41, pseudogene)
Gene: Small nuclear RNA gene on chromosome Y (18,833,729 to 18,833,890, reverse strand). Ensembl gene ENSG00000251970.
Homologues: Paralogues in human: RNU1-48P (100% identical), RNU1-128P (86% identical), RNU1-40P (86% identical), RNU1-95P (86% identical), RNU1-97P (86% identical), RNU1-1 (85% identical), RNU1-2 (85% identical), RNU1-27P (85% identical), RNU1-28P (85% identical), RNU1-3 (85% identical), RNU1-4 (85% identical), RNVU1-18 (85% identical), and 134 more.